ATF3 (activating transcription factor 3)
Description:
This protein binds the cAMP response element (CRE) (consensus: 5'-GTGACGT[AC][AG]-3'), a sequence present in many viral and cellular promoters. Represses transcription from promoters with ATF sites. It may repress transcription by stabilizing the binding of inhibitory cofactors at the promoter. [Isoform 2]: Activates transcription presumably by sequestering inhibitory cofactors away from the promoters. [Isoform 3]: Stress-induced isoform, counteracts the transcriptional repression of isoform 1.
Tractability: PROTAC: UniProt records ubiquitination sites on it; ubiquitination databases record sites on it.
Gene: Protein-coding gene on chromosome 1 (212,565,334 to 212,620,777, forward strand). Ensembl gene ENSG00000162772.
Subcellular location: Nucleus
Subcellular location (Human Protein Atlas): Basal body; Nucleoli; Nucleoplasm; Centrosome; Vesicles
Pathways (Reactome):
Cellular responses to stimuli: ATF4 activates genes in response to endoplasmic reticulum stress; Response of EIF2AK1 (HRI) to heme deficiency; Response of EIF2AK4 (GCN2) to amino acid deficiency
Immune System: Regulation of PD-L1(CD274) transcription
Gene Ontology:
Molecular function: DNA-binding transcription activator activity, RNA polymerase II-specific; DNA-binding transcription factor activity; DNA-binding transcription repressor activity, RNA polymerase II-specific; identical protein binding; protein binding; protein heterodimerization activity; protein homodimerization activity; RNA polymerase II transcription regulatory region sequence-specific DNA binding; sequence-specific double-stranded DNA binding; transcription cis-regulatory region binding; DNA-binding transcription factor activity, RNA polymerase II-specific; RNA polymerase II cis-regulatory region sequence-specific DNA binding; DNA binding
Biological process: negative regulation of transcription by RNA polymerase II; positive regulation of TRAIL-activated apoptotic signaling pathway; positive regulation of transcription by RNA polymerase II; regulation of transcription by RNA polymerase II; response to endoplasmic reticulum stress; cellular response to amino acid starvation; endoplasmic reticulum unfolded protein response; negative regulation of ERK1 and ERK2 cascade; positive regulation of cell population proliferation; positive regulation of gene expression; regulation of DNA-templated transcription
Cellular component: CHOP-ATF3 complex; nucleolus; nucleoplasm; nucleus; RNA polymerase II transcription regulator complex; chromatin
Genetic constraint (gnomAD): Loss-of-function variants: 10 observed, 19.3 expected, observed/expected ratio (o/e) 0.52, 90% interval 0.32 to 0.88. The upper end of that interval is the gene's LOEUF score, 0.88, which puts it in group 3 of 6, group 1 being the genes least tolerant of losing a copy. Missense variants: 183 observed, 234.8 expected, observed/expected ratio (o/e) 0.78, 90% interval 0.69 to 0.88. Synonymous variants: 78 observed, 92.97 expected, observed/expected ratio (o/e) 0.84, 90% interval 0.7 to 1.01.
Homologues: Orthologues: chimpanzee ATF3 (100% identical), macaque ATF3 (99% identical), guinea pig ATF3 (98% identical), pig ATF3 (98% identical), rabbit ATF3 (97% identical), dog ATF3 (97% identical), mouse Atf3 (95% identical), rat Atf3 (95% identical), tropical clawed frog atf3 (81% identical), zebrafish atf3 (72% identical), Drosophila melanogaster Atf3 (26% identical). Paralogues in human: JDP2 (44% identical), FOS (31% identical), FOSB (31% identical), FOSL1 (31% identical), FOSL2 (29% identical), BATF (20% identical), BATF3 (19% identical), BATF2 (15% identical).
Diseases named in the same sentence as ATF3 in open-access papers:
ATF3 is named in the same sentence as 322 diseases in open-access papers, as found by Europe PMC text mining. Sharing a sentence is not in itself a finding about the gene and the disease. The quoted sentences say what the papers report.
breast cancer (86 papers, 2007 to 2025). A primary or metastatic malignant neoplasm involving the breast. "This study identified three key ferroptosis-related genes (TXNIP, SLC2A1, ATF3) associated with breast cancer by integrating bioinformatics analysis and multiple machine learning algorithms, and preliminarily validated their roles through cell experiments." (PMID 38244591, 2024). "In summary, the three key ferroptosis-related genes (TXNIP, SLC2A1, ATF3) are closely associated with the development and prognosis of breast cancer." (PMID 38244591, 2024). "GOLPH3 activity was also linked to breast cancer proliferation in the activating transcription factor 3 (ATF3)-miR-590-3p pathway." (PMID 32023813, 2020). "ATF3 is a stress-inducible protein, associated with malignant transformation and breast cancer metastasis." (PMID 32023813, 2020). "(e) As a transcription factor, ATF3 modulates various target genes, and an ATF3 downstream gene-signature was identified to associate with worse outcome in a cohort of human breast cancer patients." (PMID 30373101, 2018). "But whether ATF-3 can regulate the Golgi associated genes signaling pathway during the breast cancer genesis and development remain largely unknown." (PMID 29534690, 2018). "However, our study has given limited data about role of ATF3 in breast cancer, and the diagnostic, predictive and prognostic value of ATF3 and its mechanism needs to be investigated thoroughly." (PMID 24494067, 2013). "However, this might just be the beginning; there may be many unidentified routes through which ATF3 is implicated in adaptation of breast cancer cells to hypoxia." (PMID 40016181, 2025). "Furthermore, analyses of microarray datasets derived from the metastatic organs of human breast cancer patients showed that Atf3 expression correlated with lower cytotoxic immune cell markers, consistent with the ATF3-associated immune suppression in mouse models." (PMID 30373101, 2018). "We also confirmed the induction of ATF3 in immunohistology analysis of breast tissue sections obtained from breast cancer patients." (PMID 40016181, 2025). "In this study, we identified ATF3, an adaptive response gene, to be induced in hypoxic breast cancer cells." (PMID 40016181, 2025). "By participating in multiple signaling pathways, ATF3 had an obvious proliferation on breast cancer cells and played a suppressor role in breast cancer." (PMID 39995577, 2025). "Fourth, we found that miR-216a-5p transcription is upregulated by the DOX-induced increase in ATF3 in breast cancer cells." (PMID 40360476, 2025). "Being localized on the chromosome 1q, the ATF3 gene has a >2 copy number and is observed to show an elevated protein expression in breast cancer." (PMID 40016181, 2025). "While pro- and anti-oncogenic properties for ATF3 have been identified in other cancers, only studies in breast cancer revealed opposing roles for ATF3 in the same tumour." (PMID 41198649, 2025). "As EMT and invasion are one of the aggressive phenotypes of breast cancer, we were interested to delineate the role of ATF3 in hypoxia induced invasion of breast cancer cells." (PMID 40016181, 2025). "To ensure ATF3’s function in the increased invasive potential of breast cancer, we performed overexpression of ATF3 using the ATF3 cloned pCMV3Tag1a vector." (PMID 40016181, 2025). "A prognostic model was constructed using these three genes, and the results showed that high expression of SLC2A1 is associated with poor prognosis in breast cancer patients, while low expression of TXNIP and ATF3 is associated with poor prognosis." (PMID 38244591, 2024). "In this case, decreased m6A methylation at the 5′‐UTR region of the transcription factor ATF3 mRNA and YTHDF2 downregulation in the breast cancer cells enhances the stabilization and translational efficiency of ATF3 transcripts." (PMID 39661414, 2024).
breast cancer (continued). "To investigate the effects of key ferroptosis-related genes (TXNIP, SLC2A1, and ATF3) on ferroptosis in breast cancer cells, we measured the levels of GSH, MDA, and Fe2+ in the cells." (PMID 38244591, 2024). "Among them, TXNIP and ATF3 were significantly downregulated in breast cancer tissues compared to adjacent tissues (P < 0.001), while SLC2A1 was significantly upregulated in breast cancer tissues compared to adjacent tissues (P < 0.001)." (PMID 38244591, 2024). "ATF3-transgenic mice with orthotopic breast cancer, which showed enhanced tumor growth, exhibited increased cardiac expression of periostin, CTGF, FN, SerpinA3, and CP." (PMID 38279150, 2024). "Three key ferroptosis-related genes (TXNIP, SLC2A1, ATF3) closely related to the occurrence, development, and prognosis of breast cancer were identified using machine learning algorithms." (PMID 38244591, 2024). "In breast cancer, ATF3 contributes to pro-metastatic changes in the tumor microenvironment that are enhanced by chemotherapy." (PMID 38658567, 2024). "TXNIP and ATF3 are tumor suppressor genes in breast cancer, and their upregulation can trigger the ferroptosis mechanism and suppress the growth of breast cancer cells." (PMID 38244591, 2024). "Upregulating ATF3 expression in breast cancer cells can inhibit their growth, migration, and invasion." (PMID 38244591, 2024). "We conducted in vitro transfections with siRNA-SLC2A1, TXNIP overexpression plasmids, and ATF3 overexpression plasmids to further investigate the effects of key ferroptosis-related genes on ferroptosis in breast cancer cells." (PMID 38244591, 2024). "In breast cancer, elevated ATF3 expression induces the expression of MMP13, TWIST, Slug, and Snail, thereby modulating tumor metastasis." (PMID 38586033, 2024). "The researchers started by looking at ATF3 expression levels in breast cancer cell lines with different metastatic potentials." (PMID 38046946, 2023). "Overall, this study sheds light on the function of ATF3 in breast cancer metastasis and lays the groundwork for future research into the therapeutic targeting of ATF3 or its downstream targets for breast cancer therapy." (PMID 38046946, 2023). "On the other hand, overexpression of ATF3 in highly metastatic breast cancer cells reduced metastasis in vivo, So these findings imply that ATF3 acts as a tumor suppressor in breast cancer by preventing cancer cell spread." (PMID 38046946, 2023). "The researchers next looked at the molecular processes that underpin ATF3’s function in breast cancer metastasis." (PMID 38046946, 2023). "Overexpression of activating transcription factor 3 (ATF3) increased radioresistance by inducing AKT phosphorylation in breast cancer cells." (PMID 35625825, 2022). "ATF3 protects malignant human breast cancer cells from apoptosis and promotes their metastatic potential, whereas its overexpression promotes apoptosis of PC3 human prostate cancer cells." (PMID 35283423, 2022). "such as miR-34a in head and neck cancer, or the expression of activating transcription factor 3 (ATF3) in breast cancer cell lines." (PMID 36361653, 2022). "In MCF10CA1a human breast cancer cells, ATF3 overexpression attenuates apoptosis and enhances motility when the cells are malignant, while facilitating apoptosis in untransformed cells." (PMID 35283423, 2022). "We found that Mir145 was significantly downregulated in ATF3-induced mammary tumors, and that its direct targets Klf4 and Sox2 were significantly upregulated." (PMID 33652981, 2021). "We compared the miRNA profiles from a set of four independent BK5.ATF3 mammary tumors to those of paired normal, transgenic mammary tissues using miRNA microarrays." (PMID 33652981, 2021). "In order to better characterize the BK5.ATF3 mammary tumors, we compared the DEGs we identified in the ATF3 mouse tumors to human breast cancer gene expression profiles." (PMID 33652981, 2021).
breast cancer (continued). "We present several lines of evidence supporting the idea that the dysregulated expression patterns of individual genes and enriched molecular pathways in these BK5.ATF3 mammary gland tumors are consistent with the hallmarks of basal-like human breast cancer." (PMID 33652981, 2021). "Here, we used RNA-Seq and microRNA (miRNA) microarrays to better define the molecular features of BK5.ATF3-derived mammary tumors." (PMID 33652981, 2021). "The phenotypes associated with TNBC include MAPK activation, activation of Wnt/β-catenin signaling, and a basal-like cytokeratin expression pattern, similar to the phenotypes of BK5.ATF3 mammary tumors." (PMID 33652981, 2021). "That is, Wnt signaling enables stem cell self-renewal through the EMT transition in ATF3-induced mammary tumors." (PMID 33652981, 2021). "Higher mRNA expression was detected in FN1 and LTBP1 in breast cancers than normal population, with increasing expression levels from primary to metastatic cancers, whereas ATF3 had reversed expression patterns." (PMID 33500735, 2021). "As the center of the adaptive cellular response network, ATF3 participated in tumorigenesis of colon cancer, breast cancer, prostate cancer, liver cancer and lung cancer." (PMID 34790227, 2021). "Mir145 expression was downregulated ~6-fold in ATF3-induced mammary tumors, consistent with its downregulation in human breast cancers, including basal-like and triple-negative breast cancers." (PMID 33652981, 2021). "For one thing, ATF3 can act as an oncogene to regulate the development of breast cancer and skin cancer." (PMID 34098867, 2021). "For example, ATF3 has been identified as a regulator promoting the M2 suppressive phenotypes, and ATF3 empowers macrophages to enhance breast cancer metastasis." (PMID 34921160, 2021). "The c-Jun/ATF-3 complex can bind to the matrix metalloproteinase (MMP-13) promoter AP-1 to regulate the invasion of breast cancer cells." (PMID 34787047, 2021). "This notion was supported by an upregulation of ATF3 expression in human breast cancer, prostate cancer, Hodgkin’s lymphoma, lung cancer, and spontaneous multifocal keratinocyte tumors in mice carrying a mesenchymal-specific deletion of CSL/RBP-Jκ." (PMID 35052581, 2021). "ATF3 expression is upregulated in breast cancer after radiation therapy, and the transcription factor has been involved in the radio-resistance of breast cancer through the PI3K/AKT signaling pathway." (PMID 32922364, 2020). "Knockdown of ATF-3 expression in MDA-MB231 breast cancer cells decreases cell number, cell migration, and the expression levels of invasive and metastatic genes, such as MMP-13 and Runt-related transcription factor 2 (Runx2)." (PMID 32922364, 2020). "This study proposes ATF3 as a novel mediator of endocrine resistance development in breast cancer and elucidates its role in the regulation of downstream pathways activities." (PMID 33050633, 2020). "In breast cancer and particularly in resistance to treatments, ATF3 expression has been described as mediated by pAKT in radioresistance, mostly by JNK pathway in chemoresistance." (PMID 33050633, 2020). "In a spontaneous metastasis mouse model produced by fat-pad injection of cancer cells, paclitaxel remarkably aggravated breast cancer metastasis in WT mice but only slightly affected ATF3 KO mice." (PMID 32922364, 2020). "ATF3 expression is upregulated in a large number of human breast cancers, possibly owing to the amplification of the ATF3 gene localized within the chromosome 1q amplicon, which is the most commonly amplified region in breast cancer." (PMID 32922364, 2020).
breast cancer (continued). "ATF3 was shown to be involved in radio-resistance of breast cancer via the PI3K/AKT signaling pathway." (PMID 32922364, 2020). "ATF3 is upregulated in the stromal compartment of several types of cancer, including colon, lung, and breast cancers." (PMID 32922364, 2020). "In summary, ATF3 can upregulate genes involved in breast cancer cell metastasis, including MMP13, FN, TWIST1, Slug, and Snail, in MCF10CA1a cells." (PMID 32922364, 2020). "Ectopically expressing ATF3 can mediate the expression of markers of the epithelial-to-mesenchymal transition (EMT) in breast cancer cells." (PMID 31410216, 2019). "It was found out that the expression level of ATF3 in breast cancer tissues which had received radiotherapy was strongly higher than that in adjacent tissues (P < .01)." (PMID 30117642, 2018). "The protein expression of ATF3 was assessed by Western blot and the protein expression of ATF3 was also markedly up‐regulated in breast cancer cell lines (all P < .05)." (PMID 30117642, 2018). "(a) Atf3 functions as an oncogene in malignant breast cancer cells, such as increasing the TIC features of cancer cells and promoting tumor formation." (PMID 30373101, 2018). "This study was designed to research the influence of activating transcription factor 3 (ATF3) on the radioresistance of breast cancer." (PMID 30117642, 2018). "Subsequent work collectively provided several lines of evidence supporting a role of Atf3 in breast cancer." (PMID 30373101, 2018). "In this present study, we detected that breast cancer radioresistance was enhanced when the ATF3 expression was up‐regulated, resulting in less breast cancer cell apoptosis, decreased G2/M phase block and more activated PI3K/Akt signalling pathway." (PMID 30117642, 2018). "In accordance with all the reports above, we have decided to disclose the relationship between the radioresistance of breast cancer cells and the expression of ATF3 in the PI3K/Akt signalling pathway." (PMID 30117642, 2018). "We also found that ATF-3 repressed miR-590-3p expression to modulate miR-590/GOLPH3 pathway to regulate breast cancer cells proliferation." (PMID 29534690, 2018). "In summary, breast cancer stroma-related genes, including JUN, FOS, ATF3, STAT1, COL1A1 and FN1, were all associated with tumor invasion and metastasis." (PMID 30237810, 2018). "In this study, we demonstrated the regulatory function of ATF-3/miR-590-3p/GOLPH3 signaling pathway in breast cancer on regulating the proliferation of breast cancer cells." (PMID 29534690, 2018). "As it was found out, ATF3 expression was significantly higher in breast cancer tissues and cells after radiation therapy." (PMID 30117642, 2018). "In conclusion, JUN, FOS, ATF3 and STAT1 have been reported to be associated with breast cancer invasion and directly or indirectly participate in ECM remodeling." (PMID 30237810, 2018). "For example, ATF3 plays an oncogenic role in malignant cell growth in Hodgkin’s lymphoma, and in prostate, skin and breast cancer cells." (PMID 29966001, 2018). "By repressing miR-590-3p, ATF-3 modulated the miR-590/GOLPH3 signaling pathway on regulating proliferation of breast cancer cells." (PMID 29534690, 2018). "As a proto-oncogene, ATF3 expression is elevated in human breast cancer, malignant human prostate cancer, malignant Hodgkin's lymphoma, and squamous cell carcinoma." (PMID 28860159, 2017). "It was reported that EGR-1 can inhibit the growth of hepatocellular carcinoma cell lines and suppress the transformation activity in fibrosarcoma and breast carcinoma, ATF3 and KLF4 were reported as tumor suppressors in HCC." (PMID 29254483, 2017). "In breast cancer, ATF3 enhances cancer’s cell-initiating features and is associated with activation of the canonical Wnt/β-catenin pathway." (PMID 27043582, 2016).